SNORD114-2 (small nucleolar RNA, C/D box 114-2)
Synonyms: 14q(II-2)
Gene: Small nucleolar RNA gene on chromosome 14 (100,951,856 to 100,951,933, forward strand). Ensembl gene ENSG00000200823.
Gene Ontology:
Biological process: RNA processing
Cellular component: nucleolus
Homologues: Orthologues: chimpanzee SNORD114-2 (99% identical). Paralogues in human: SNORD114-1 (76% identical), SNORD114-11 (74% identical), SNORD114-3 (74% identical), SNORD114-12 (72% identical), SNORD114-14 (72% identical), SNORD114-13 (71% identical), SNORD114-21 (71% identical), SNORD114-23 (71% identical), SNORD114-26 (71% identical), SNORD114-15 (69% identical), SNORD114-17 (69% identical), SNORD114-18 (69% identical), and 26 more.